VCL (vinculin)
Diseases named in the same sentence as VCL in open-access papers (continued):
Sharing a sentence is not in itself a finding about the gene and the disease.
infection (continued). "For validation of outlined interactions and to legitimate calculated miR-29a-target interactions and to prove biological significance, we examined the expression of miR-29a, AKT3, BAIAP2, COL4A1, VCL, CAV2 and CDC42 over the course of infection by means of RT-qPCRs." (PMID 23826261, 2013). "An analysis of Lactobacillus-precolonized Tv G3-exposed cells revealed that the decreases in the number and size of vinculin-positive FAs began in hour 18 of infection, whereas these changes were visible as early as hour 6 of infection in non-precolonized Tv G3-exposed cells." (PMID 36355522, 2022). "However, β-actin and vinculin showed no significant changes in protein level for all treatment conditions at 24 h post-infection, compared with the mock control cells." (PMID 34696472, 2021). "Interestingly, we find that Schlafen11 is functional in the absence of infection and reduces protein production from certain non-viral (GFP) and even host (Vinculin and GAPDH) transcripts." (PMID 28027315, 2016). "The importance of SNX1, VCL and PAK1 for infection of HeLa cells with MHV could not be confirmed (grey)." (PMID 25375324, 2014).
bacterial infection (2 papers, 2014 to 2023). "Our results suggest that vinculin binds to Rab5 and that these two molecules cooperatively enhance bacterial infection and the inflammatory response." (PMID 24466349, 2014). "Bacterial infection, or stimulation with PAM, induced a significant signal in the reporter cells, confirming the inducible interaction between TLR2 and VCL." (PMID 37023213, 2023). "Taken together, our results show that bacterial infection, or PAM stimulation, induces TLR2 interaction with VCL through specific residues of the TIR domain outside the BB loop." (PMID 37023213, 2023).
kidney disease (2 papers, 2018 to 2022). "With the advent of whole-exome and whole-genome sequencing across an ever-increasing number of clinical cohorts with kidney disease, genetic variants in vinculin may shed further light on the role of vinculin in human disease." (PMID 29241625, 2018).
myopathies (2 papers, 2018 to 2022). "Vinculin expression was also increased in desmin-related myopathy patient muscles." (PMID 35350386, 2022). "Mutations in the genes encoding RSU1, tensin and vinculin have not been linked to muscle myopathies, but mutations in filamin are linked to myofibrillar myopathies." (PMID 30028294, 2018).
cardiovascular diseases (1 paper, 2024). "Targeting vinculin, Fak, or syndecans may have therapeutic potential in promoting or inhibiting angiogenesis in various physiological and pathological conditions, such as cardiovascular diseases." (PMID 38247492, 2024).
vasculopathy (1 paper, 2022). "Therefore, vinculin overexpression in SSc may give rise to anti-vinculin antibodies, which may contribute to the development of SSc vasculopathy." (PMID 35876914, 2022).
VCL also shares sentences with these, for which no sentence is quoted: non-small cell lung carcinoma (4 papers); heart disease (2); Huntington disease (2); membranous nephropathy (2); osteoarthritis (2); systemic sclerosis (2); acute megakaryoblastic leukemia (1); acute myeloid leukemia (1); acute myocardial infarction (1); age-related macular degeneration (1); Amoebiasis (1); amyloid (1); and glucocorticoid deficiency (1); Arrhythmia (1); arrhythmogenic right ventricular cardiomyopathy (1); asthenozoospermia (1); atrial fibrillation (1); autoimmune disease (1); benign prostate hyperplasia (1); cardiac hypertrophy (1); cervical squamous cell carcinoma (1); Chagas disease (1); chondrosarcoma (1); chromophobe-type renal cell carcinomas (1); clear cell renal cell carcinoma (1); cleft lip (1); cleft palate (1); colitis (1); collecting duct carcinoma (1); Constipation (1).
A further 38 diseases each share a sentence with VCL in 1 paper.